DPP4 (dipeptidyl peptidase 4)
Diseases named in the same sentence as DPP4 in open-access papers (continued):
Sharing a sentence is not in itself a finding about the gene and the disease.
infection (continued). "This suggests for the 1st time, to the best of our knowledge, that salivary DPP-4 may offer reliable and more advantageous diagnostic potential for both OSCC and OPMLs due to its less invasive collection method, lower risk of infection, and simpler sampling process compared to serum DPP-4." (PMID 39390508, 2024). "MERS-CoV initiates infection in humans by binding the S protein to the cellular receptor, dipeptidyl peptidase-4 (DPP4)." (PMID 40525828, 2025). "The inability of most merbecoviruses to engage DPP4 has hindered the development of robust infection models, limiting our understanding of their entry mechanisms and our ability to develop and evaluate the efficacy of antiviral therapeutics and vaccines." (PMID 40162213, 2025). "Not all but some of these merbecoviruses are known to bind to the cellular receptor DPP4 expressed on host cells to initiate infection in the same way as MERS-CoV." (PMID 40740328, 2025). "Recently, the neonatal Fc receptor (FcRn) was identified as a receptor for classical HAstV, and the dipeptidyl peptidase-4 (DPP4) as an entry factor for infection." (PMID 40680075, 2025). "Further experiments using virus infectivity and attachment assays, along with Nt-MAbs targeting HAstV-1, suggest that the binding sites for FcRn and DPP4 are spatially proximal on the viral spike, defining a functional domain for cell infection." (PMID 40680075, 2025). "It has been shown that astrocytes express DPP4, however, the group was unable to directly demonstrate DPP4’s role in direct infection." (PMID 38793666, 2024). "This is attributed to (i) large differences in the MERS and SARS/SARS-2 spike sequences (sequence identity less than 35%), and (ii) different host receptors used for infection, with DPP4 for MERS and hACE2 for both SARS and SARS-2." (PMID 38543849, 2024). "In comparison to DPP4 alone, the infection levels in cells co-transfected with DPP4 and TMPRSS2 are significantly higher, underscoring the critical role of TMPRSS2 in facilitating viral entry." (PMID 40295839, 2024). "Looking at viral internalization in both human and non-human hosts, it was discovered that MERS-CoV pseudovirus enabled single-cycle infection in different cell types expressing dipeptidyl peptidase-4 (DPP4), which was confirmed as the receptor for MERS-CoV." (PMID 38791226, 2024). "In comparison, the highly pathogenic MERS-CoV utilizes the dipeptidyl peptidase 4 (DPP4), an exonuclease present in cells of the upper airway and kidney, for infection." (PMID 38399953, 2024). "Second, we determined that the most likely primary receptor for infection within astrocytes and pericytes is DPP4, which is also the receptor for MERS-CoV." (PMID 38793666, 2024). "In particular, the human lower respiratory tract shows a higher expression of DPP4, which can result in an increased severity of infection but also serves as a limiting factor for transmission." (PMID 40295839, 2024). "The reduced infections were correlated with the surface expression and S1-Fc binding of the different mutant DPP4." (PMID 40295839, 2024). "The affinity of the MERS-CoV S RBD for human DPP4 is ~17 nM, but low-affinity goat and bat receptors can also hypersensitize cells to infection when an S-cleaving protease is present." (PMID 38829136, 2024). "In our previous work, the primary mechanism of the peptide was to block the S protein’s receptor-binding region from interacting with DPP4, thus acting preventively against infection." (PMID 39065742, 2024). "Overall, our inhibitor studies suggest that DPP4-mediated β-cleavage is an important driver of PrPSc accumulation in these cell-based infection models." (PMID 36574660, 2023). "A total of 16 DEmRNAs (e.g. dpp4, crp and gnas) were commonly identified at the three infection stages." (PMID 36991462, 2023).
infection (continued). "The authors showed that in people resistant to infection, the expression of DPP-4 in CD4+ T cells was significantly increased compared to HIV-negative and unexposed people (p = 0.0003)." (PMID 35330038, 2022). "After the coexpression of ACE2 and DPP4 was confirmed, the cells were applied to same infection assay." (PMID 36152751, 2022). "Reducing the abundance of CD147 or the activity of DPP4 reduced infection, whereas increasing expression of these receptors promoted infection, suggesting a role in viral entry or propagation." (PMID 35858406, 2022). "In SARS-CoV-2, a functional network analysis revealed that DPP4 is required in viral processes for viral entry and infection." (PMID 36145576, 2022). "Here, we demonstrated a strong reduction of inflammasome pathways after neutralization of the infection by Fab IgG 15033-7 or DPP4 peptide treatment." (PMID 35406799, 2022). "The viral spike (S) glycoprotein of both SARS-CoV and SARS-CoV-2 uses angiotensin-converting enzyme 2 (ACE2) as a receptor to mediate cell entry, while MERS mediates infection by binding to the dipeptidyl peptidase 4 (DPP4)." (PMID 35455942, 2022). "The infection of ciliated cells, despite the fact that ciliated cells represent only a small proportion of the DPP4-positive cell population, highlights the possibility of additional factors that can promote MERS-CoV binding and entry." (PMID 35059374, 2021). "Using primary airway epithelia from human donors as a model, we found that DPP4 abundance correlated positively with infection and viral replication, and appeared to influence pathogenesis as assessed by cell sloughing/disruption of the epithelium." (PMID 35059374, 2021). "In particular, we sought to better understand how variation in DPP4 at the level of the individual contributes to infection outcomes." (PMID 35059374, 2021). "In summary, these data together with previous findings strongly suggested that DPP4 has the great potential in mediating the infection of SARA-Cov-2." (PMID 33614513, 2021). "We noted that the titers of released virus at 1 day post infection correlated positively with cellular DPP4 abundance, suggesting that cellular DPP4 abundance at least partly determines individual susceptibility to MERS-CoV." (PMID 35059374, 2021). "MERS‐CoV initiates infection of bronchial epithelial cells via binding to dipeptidyl peptidase 4 (DPP‐4) receptor and spreads, entering the lung parenchymal cells." (PMID 34141446, 2021). "Overall, a 1 L suspension of Sf9 cells (1.2–2.2 × 106 cells/mL) was infected at a multiplicity of infection (MOI) of 1 and harvested 7 days post-infection for large-scale DPP4 protein expression." (PMID 33218025, 2020). "Of most direct relevance to the possible use of ADA against early infection by SARS-CoV-2 are findings that MERS-CoV entry and infection were prevented with exogenous ADA outcompeting MERS-CoV binding to DPP4." (PMID 33324223, 2020). "Contrarily, the proposed mechanism of hepatic injury with MERS-CoV involves dipeptidyl peptidase-4 (DPP-4) as its entry receptor to establish infection in the hepatocytes." (PMID 32903492, 2020). "A nested case-control study of the WHO database Vigibase also found increased reporting of infections for individuals using DPP4 inhibitors compared with users of biguanides (OR 2.3 (95% CI 1.9, 2.7)." (PMID 33261058, 2020). "When followed over a period of two days post infection it was observed that MERS-CoV replication in BHK-21 cells expressing human DPP4 was significantly reduced when DPP4 contained either K267E or A291P." (PMID 31964246, 2020). "Genetic variations in DPP4 block interactions between MERS-CoV spike protein and those variations cause species barriers to infection." (PMID 33324223, 2020). "DPP4 expression was optimised by varying the quantity of virus for infection and the time to harvest." (PMID 33218025, 2020).
infection (continued). "Second, relative to Mono-Nb, the engineered oligomeric Nbs strongly blocked RBD binding to MERS-CoV receptor DPP4, which is involved in a key step of viral entry and infection, thereby more effectively blocking entry of MERS-CoV into its target cells." (PMID 30791410, 2019). "The MERS-CoV pseudovirus allows for single-cycle infection of a variety of cells expressing DPP4, and results are consistent with those from a live MERS-CoV-based inhibition assay." (PMID 30562987, 2018). "The hDDP4 (human DPP4) receptor has been previously identified as the receptor for MERS-CoV human infection." (PMID 29868035, 2018). "MERS-CoV pseudovirus expressing S protein, which allows for single-cycle infection in cells expressing receptor DPP4, can be used for screening MERS-CoV fusion/entry inhibitors." (PMID 30562987, 2018). "We observed a striking lower plasma activity of soluble DPP4 in TB patients compared to healthy individuals further supporting the concept that CXCL10 truncation is an early event occurring at the site of infection." (PMID 30026741, 2018). "Transnasal infection with MERS-CoV following adenoviral transduction of human DPP4 yielded an expansive, interstitial pneumonia with severe alveolar epithelial cell necrosis and infiltration of mainly macrophages, lymphocytes, and fewer neutrophils." (PMID 29155867, 2017). "We confirmed that the assay measured viral entry via the MERS-CoV receptor, DPP4, by demonstrating that HEK 293 cells required DPP4 expression on their surface for efficient infection and that soluble DPP4 or anti-DPP4 antibody prevented infection." (PMID 26218507, 2015). "Human, macaque, horse, and rabbit DPP4 have been suggested to be able to bind MERS-CoV and therefore are susceptible to infection." (PMID 26075284, 2015). "Although representing an advance in the development of a viable animal model for MERS-CoV, transduced mice are still limited in their relevance to human infection by the inconsistent expression of the transduced protein, in this case human DPP4." (PMID 26218507, 2015). "Considering the diverse functions of DPP4, the safety of long-term usage of DPP4i on immune function such as antitumor and anti-infection was questioned." (PMID 26075284, 2015). "Our results demonstrated that the generated MERS-CoV pseudovirus allows for single-cycle infection of a variety of cells expressing dipeptidyl peptidase-4 (DPP4), the confirmed receptor for MERS-CoV." (PMID 23978242, 2013). "Other factors, such as the transmembrane protease serine 2 (TMPRSS2) which is most abundantly expressed in multiciliated cells of human airway tissues, may also contribute to the infection of these cells in consort with DPP4." (PMID 40048293, 2025). "In fact, Dpp4 is secreted by A. fumigatus and may affect the overall physiology of the host in the setting of infection, i.e., the enzyme could play a role in the colonization step of host tissues." (PMID 40985416, 2025). "Given these dynamics, monitoring zoonotic reservoirs remains critical—not only to detect viruses already using key human receptors such as ACE2, APN, DPP4, or TMPRSS2, but also to identify emerging variants with pandemic potential before widespread human infection occurs." (PMID 40981424, 2025). "Given that DPP4 is a key mediator of chemokine/cytokine responses and T-cell activation aside from being the receptor for MERS-CoV entry, chimeras of human and mouse DPP4 could affect infection, replication, pathogenesis, and the immune response." (PMID 39882872, 2025). "We conclude that DPP4 inhibition may be a safe and potent means to curb immune responses to surgery or infection, resulting in a preservation of vascular integrity that translates into organ protection and improved clinical outcomes." (PMID 40817204, 2025). "There also remains a debate about the role of DPP4 in receptor-mediated infection." (PMID 38793666, 2024).
infection (continued). "Furthermore, transient transfection of porcine and murine DPP4-expressing cells promoted infection after the cells were able to interact with PHEV S1-RBD." (PMID 38829136, 2024). "To determine the effects of ACE2 depletion in HUVECs or DPP4 depletion in astrocytes and pericytes on infection with SARS-CoV-2, we first transduced the shLentiviruses on their respective cells for 48 h at the 1 IU/cell and then infected cells with 1 MOI SARS-CoV-2." (PMID 38793666, 2024). "MERS-CoV uses human dipeptidyl peptidase 4 (hDPP4) as a receptor for infection." (PMID 38675818, 2024). "Furthermore, the partial reduction of infection in cells endogenously expressing both DPP4 and TMPRSS2 following treatment with a TMPRSS2 inhibitor, in contrast to the lack of inhibition in cells expressing only DPP4, confirms the dual entry path of MERS-CoV." (PMID 40295839, 2024). "In SARS-CoV-2 infected astrocytes, pre-transduction with shDPP4 lentivirus significantly reduced virion production (34 PFU/mL) vs. shScr lentivirus (231 PFU/mL) vs. naïve astrocytes (348 PFU/mL), demonstrating a pronounced effect of DPP4 in permitting a productive infection from SARS-CoV-2." (PMID 38793666, 2024). "Furthermore, direct infection of microglia by SARS-CoV-2 occurred via dipeptidyl peptidase 4 (DPP4) binding." (PMID 38793545, 2024). "In the present study, dpp4 was significantly upregulated at the early stages of infection." (PMID 36991462, 2023). "Additionally, there is a predicted binding between the S1 Spike protein of SARS-CoV and DPP4, potentially facilitating the infection of epithelial cells." (PMID 37893528, 2023). "The dpp4 was involved in the immune system process (GO:0002376), regulation of cytokine production (GO:0001817) and lymphocyte activation (GO:0046649) at three stages of infection." (PMID 36991462, 2023). "Also, 16 DEmRNAs (e.g. crp, dpp4 and gnas) were commonly detected at the three infection stages, of which the expression level of C-reactive protein (crp) was significantly downregulated at 24 hpi and 36 dpi." (PMID 36991462, 2023). "Consequently, it is recognized by cluster of differentiation 26, CD26 (also known as DPP4); which assists in the infection of the host cells." (PMID 35721786, 2022). "A possible role of antidiabetic therapy cannot be excluded and special interest has been devoted to dipeptidyl-peptidase 4 (DPP4) inhibitors, as DPP4 was one of the receptors involved in the infection from a related coronavirus (Middle East Respiratory Syndrome—Coronavirus)." (PMID 32776197, 2021). "The idea that genetic variation at the DPP4 locus may contribute to MERS-CoV susceptibility and infection outcomes is supported by literature." (PMID 35059374, 2021). "At present, it is unknown whether these mechanisms can also be applied to COVID-19 and whether treatment of DM with DPP4 inhibitors in clinical practice affects the course of the infection." (PMID 34830623, 2021). "It has been also found that the susceptibility or resistance to the infection of different cell lines directly correlates with the presence or absence of CD26/DPP4 expression." (PMID 34239932, 2021). "The S1 subunit (N-terminal) of the surface protein facilitates binding to the ACE2 receptor while the S2 subunit (C-terminal) mediates host cell entry through the binding of the viral S protein to human dipeptidyl peptidase 4 (DPP4), marking onset of infection." (PMID 33654512, 2020). "In vitro expression of human and bat DPP4 in previously non-susceptible cells without previous DPP4 expression subsequently enabled infection of those cells by MERS-CoV." (PMID 32490731, 2020). "These antibodies inhibit RBD from binding the host receptor dipeptidyl peptidase 4 (hDPP4; also known as CD26), An alternative strategy is to use virus-specific therapeutic human antibodies that can be rapidly developed to neutralize the virus during infection." (PMID 32384116, 2020).
infection (continued). "In humans, abortive infection of lymphocytes induces apoptosis by activation of both the intrinsic and extrinsic pathway of apoptosis and is accompanied by massive downregulation of DPP4 on the surface of infected T cells." (PMID 29950581, 2018). "It is thus tempting to speculate on repurposing of DPP4 inhibitors for host-directed therapy of human TB to improve migration of the relevant cells to the infection site." (PMID 30026741, 2018). "MERS-CoV needs dipeptidyl-peptidase-4 (DPP-4) receptors on host cells for infection." (PMID 30288197, 2018). "Furthermore, we also report here DPP4 levels through a longitudinal analysis, starting prior to initial infection and revealing that the sDPP4 levels recovered only partially after PHI, and remained lower than in healthy donors." (PMID 29987877, 2018). "In conclusion, we found no increased risk of infection in T2DM patients using DPP4 inhibitors compared to T2DM patients using other NIADs." (PMID 26468883, 2015). "The most recent example is the conserved receptor Dipeptidyl-peptidase-4 for MERS-coronavirus that allows infection of bat cell lines, not only originating from the presumed reservoir host, bats of the family Vespertilionidae, but across several other bat families." (PMID 24454736, 2014). "Furthermore Ad-GFP-Slfn3 infection of Caco-2 cells also increased expression of the differentiation markers villin and Dpp4 compared to control (n = 3, p<0.01)." (PMID 24244554, 2013). "Moreover, it has been revealed that at the S proteins of at least two merbecoviruses, BtCoV/Ii/GD/2014–422 (BtCoV-422; a MERSr-CoV) and MjHKU4r-CoV (MjHKU4r-CoV; an HKU4r-CoV), both detected in a bat and a pangolin respectively, can use human DPP4 for infection." (PMID 40740328, 2025). "Interestingly, the infectivity of the three serotypes in double-KO Caco-2 cells was below the detection limit of our infection assay (of about 102 ffu/ml), strongly suggesting that both FcRn and DPP4 are necessary and sufficient for classical HAstV infection, at least in Caco-2 cells." (PMID 40680075, 2025). "This novel peptide (named DPP4-derived), conceived as an endogenous “drug”, is capable of targeting the latest tested variants with a high affinity, reducing the VSV* DG-Fluc pseudovirus Omicron’s infection capacity by up to 14%, as revealed by in vitro testing in human Calu-3 cells." (PMID 39065742, 2024). "When examining the tissue responses to infection at the single-cell level, we identified that Dpp4+Pi16+ interstitial preadipocytes upregulate Il17ra in response to T. brucei infection, indicating that the capacity of these cells to sense IL-17 signalling is augmented during infection." (PMID 37923768, 2023). "Therefore, DPP4 inhibitors could be used to block the virus from entering cells and preventing infection." (PMID 37896834, 2023). "Hence, similar to other adipokines, DPP-4 may be both beneficial or harmful depending on the temporal nature of infection and response." (PMID 35318939, 2022). "Successively, for testing the efficiency of DPP4 peptides (specifically DPP4270–295 and DPP4318–343), for inhibition of the entry driven by WT and variant S proteins (i.e., D614G, B1.1.7, B1.351, and P1), pseudoviruses carrying either SARS-CoV-2 WT or those variants were used for the infection." (PMID 34452531, 2021). "Our results revealed that cells from different airway epithelial donors express variable levels of DPP4 protein, and that this variability translates to measurable differences in viral replication and pathogenesis as well as host innate immune responses during infection." (PMID 35059374, 2021). "Thus, the delayed increase in type I IFN expression we observed in HAE at 5 days post infection may contribute to disease pathology in humans, particularly for individuals with relatively high levels of DPP4." (PMID 35059374, 2021).